PURPL (p53 upregulated regulator of p53 levels)
Diseases named in the same sentence as PURPL in open-access papers (continued):
Sharing a sentence is not in itself a finding about the gene and the disease.
lymph node metastasis (2 papers, 2021 to 2023). "Upon individual analyses and comparisons of the current OSC specimens, we discovered that PURPL upregulation and miR-363-3p downregulation were associated with advanced clinical stage and developed lymph node metastasis, respectively." (PMID 37781085, 2023). "Positive relations were noted between PURPL expression and clinical stage and lymph node metastasis of EOC." (PMID 34405027, 2021). "Binary logistic regression analysis was used to analyze high risk factors of recurrence and death of 65 EOC patients, related factors including PURPL expression, miR-338-3p expression, age, clinical stage, histological grade, histological classification, ascites and lymph node metastasis." (PMID 34405027, 2021). "The expressions of PURPL were significantly higher in the EOC patients with more advanced clinical stage and developed lymph node metastasis." (PMID 34405027, 2021).
ovarian serous cystadenocarcinoma (2 papers, 2021 to 2023). A malignant serous cystic epithelial neoplasm arising from the ovary. "In 32 TCGA PanCancer Atlas studies including 10967 samples, amplifications of PURPL were detected in several malignant human tumor tissues including ovarian serous cystadenocarcinoma tissues." (PMID 34405027, 2021).
aneuploidy (1 paper, 2024). Chromosomal disorder consisting of the presence a chromosomal abnormality in which there is an addition or loss of chromosomes within a set. "For example, reversine-induced CIN or aneuploidy and PURPL expression are higher as compared to CIN or aneuploidy triggered by other stimuli." (PMID 39763585, 2024).
B-cell Lymphoma (1 paper, 2025). "Key genes such as PAK3, LINC00487, AID, PURPL, and BCL2 were among the most dysregulated, highlighting TIMAP’s role in critical oncogenic pathways in B-cell Lymphoma." (PMID 41170526, 2025).
serous cystadenoma (1 paper, 2023). A serous neoplasm in which the cysts and papillae are lined by a single layer of cells without atypia, architectural complexity or invasion. "We identified overexpression of PURPL, underexpression of miR-363-3p, and upregulation of ADAM10 in the OSC tissues enrolled for this study, in contrast to normal ovarian tissues and serous cystadenoma tissues." (PMID 37781085, 2023).
cancer (12 papers, 2020 to 2025). A tumor composed of atypical neoplastic, often pleomorphic cells that invade other tissues. "PURPL expression is evidently leveled up in GC tissues as compared with normal adjacent tissues, the profile level of PURPL positively correlates with the tumor size and pathological grade of the cancer, and it functions as an underlying molecular marker for GC diagnosis." (PMID 35012438, 2022). "Many of the other lncRNAs, such as LINC01220, CYTOR, LINC00910, LINC00511, PURPL, and MZF1-AS1, have been described in association with different types of cancer, mainly with proliferation and migration of the tumour cells." (PMID 38616192, 2024). "PI3K or NF-κB inhibition considerably weakens the cancer-promoting function mediated by lncRNA PURPL." (PMID 35012438, 2022). "Inhibition of PI3K or NF-κB could conspicuously mitigate lncRNA PURPL-mediated cancer-promoting effects and lncRNA PURPL expression." (PMID 35012438, 2022). "The expression levels of PURPL are varied in different types of cancer compared with corresponding normal tissues, which may indicate its diverse roles in different cancers." (PMID 34759263, 2021). "Additional ncRNAs in this group have been studied in the context of cancer (e.g., THAP9-AS1, PURPL, OTUD6B-AS1), transcriptional regulation (e.g., KCNQ1OT1), and chromatin structure." (PMID 41369348, 2025). "Others, such as LINC01220, CYTOR, LINC00910, LINC00511, PURPL, and MZF1-AS1, have been described so far only in cancer." (PMID 38616192, 2024). "Long non-coding RNA (lncRNA) PURPL (also referred to as LINC01021) has been demonstrated to influence malignant GC behaviors and partake in other cancers." (PMID 35012438, 2022). "All the discoveries signified that PURPL elevated ZBTB7A’s expression and initiated the PI3K/AKT/NF-κB pathway, hence bringing into full play its substantial cancer-promoting function." (PMID 35012438, 2022). "In order to find the molecular mechanism by which PURPL can regulate nuclear morphology or chromosomal stability, we focused on MDM2 for the following reasons: The MDM2 gene was subsequently found to be amplified in cancer." (PMID 39763585, 2024). "With the exception of the lncRNAs SCAT1, LINC00320, PURPL, and TP53TG1, associated with the risk of certain types of cancer or genetic diseases, no other associations with human disorders were found." (PMID 36768581, 2023).
tumor (11 papers, 2020 to 2025). "However, it should be noted that although CIN or aneuploidy can be the underlying mechanism for PURPL-promoted tumor growth, the mechanistic connections between these phenotypes are not established in this study." (PMID 39763585, 2024). "RT-PCR ascertained miR-137 and ZBTB7A mRNA expressions in the AGS and MKN-45 cell models with PURPL overexpression and the xenograft tumor model." (PMID 35012438, 2022). "After the 9th day, PURPL depletion markedly inhibited tumor growth compared with the control group and led to evidently smaller tumor mass at the end of the evaluation period." (PMID 34759263, 2021). "To dig deeper into the function of lncRNA PURPL overexpression in vivo, we inoculated the suspension of AGS cells with overexpression of lncRNA PURPL into the back of the mice on the right and posterior sides to establish a xenograft tumor model." (PMID 35012438, 2022). "To better understand the regulatory correlation between PURPL and the PI3K/AKT/NF-κB pathway, we implemented Western blot and immunofluorescence to reveal the profile of the PI3K/AKT/NF-κB axis in the nude mouse tumor tissues." (PMID 35012438, 2022).
PURPL also shares sentences with these, for which no sentence is quoted: osteosarcoma (2 papers); benign ovarian tumor (1); cardiovascular disorder (1); colorectal tumors (1); cutaneous melanoma (1); genetic diseases (1); lung carcinoma (1).